FASN (fatty acid synthase)
Diseases named in the same sentence as FASN in open-access papers (continued):
Sharing a sentence is not in itself a finding about the gene and the disease.
cancer (continued). "In cancers, the upregulation of FASN is consistent with excess metabolism of arachidonic acid (AA) that can be converted to prostaglandins by the COX-dependent pathway." (PMID 32422889, 2020). "G28 inhibits the fatty acid synthase (FASN) enzyme of cancer cells, which seems to be responsible for cancer cells drug resistance." (PMID 32952942, 2020). "CSCs play an important role in cancer progression and are often reported to have increased activity of FASN." (PMID 32670883, 2020). "One of these compounds, TVB-2640, has become the first FASN inhibitor to enter clinical trials for patients with cancer, and initial reports have demonstrated encouraging responses in patients with non-small cell lung, ovarian, and breast cancer." (PMID 33083663, 2020). "There is limited knowledge on the impact of ER-stress on lipid metabolism, particularly between FASN and ER in cancers." (PMID 32872164, 2020). "Inhibition of FASN with EGCG has been considered for several cancer types, including prostate, lung, breast, and colorectal cancer, for which several phase 2 and phase 3 clinical trials are ongoing." (PMID 32947972, 2020). "Overexpression of fatty acid synthase (FASN), a key fatty acid synthesis enzyme, has also been reported in several cancer types and associated with poor prognosis and resistance to chemotherapy." (PMID 32312965, 2020). "Previous studies found that FASN is strongly upregulated in cancers such as prostate cancer, colorectal cancer, bladder cancer, ovary cancer, and lung cancer." (PMID 32714863, 2020). "Several FASN inhibitors have been developed for cancer therapy during the past decades, such as orlistat." (PMID 32695216, 2020). "HER2, which is frequently overexpressed in breast cancer and other cancers, can stimulate the expression of FASN via the PI3K/Akt/mTOR and Ras/Raf/MAPK pathway." (PMID 33364199, 2020). "All these studies, inevitably describe FASN as an important metabolic target in cancer therapeutics." (PMID 32670883, 2020). "Fatty acid synthase (FASN) supports cancer cells to resist oxidative stress and limits the absorption of chemotherapy drugs." (PMID 32698888, 2020). "Overexpression of FASN has been shown for a number of cancers, such as lung, prostate, ovarian and colon." (PMID 33415069, 2020). "The up-regulation of fatty acid synthase (FASN) and subsequent enhanced de novo synthesis of fatty acids have been described as a frequent event in cancer cells." (PMID 32596159, 2020). "FASN was downregulated most significantly among all those downregulated genes, which is reported to be crucial for the survival of cancer cells." (PMID 32714863, 2020). "Due to its poor oral bioavailability, intravenous formulations of orlistat are under development and have shown efficacy in preclinical models, while other FASN inhibitors continue to be tested as anti-cancer drugs in clinical trials." (PMID 32811515, 2020). "In this regard, TRIM21 functions as a tumour suppressor, as FASN is overexpressed in various types of cancer." (PMID 32225170, 2020). "Novel FASN inhibitors developed by Sagimet Biosciences show anti-cancer activity in lung, prostate, ovarian, and colon cancer models in vitro and in vivo, and are currently being tested in phase I/II clinical trials." (PMID 32850342, 2020). "The palmitoylation of FASN was first validated because its link to lipid metabolism is well established in many cancer types, including BC 33,36,54,55." (PMID 32792852, 2020). "Regulation of FASN expression and lipid biosynthesis has been studied in detail in cancer, and a variety of compounds have been developed that directly interfere with FASN enzyme activity and block de novo FA synthesis." (PMID 32913236, 2020). "Elevated FASN levels have been reported in a variety of cancers, including liver, prostate, breast, ovarian, endometrial and pancreatic cancers." (PMID 32641978, 2020).
cancer (continued). "In terms of therapeutically targeting dysregulated lipid metabolism in cancer, FASN has arguably received the most widespread interest, and this is not surprising given its multifaceted roles in supporting both anabolic metabolism and oncogenic signalling." (PMID 31819192, 2020). "In many cancer types, FASN is overexpressed, and thus the majority of fatty acids in these cells are assumed to be derived from DNL." (PMID 33302403, 2020). "Considering this point that tumor cells survival is mostly depended on FASN-mediated de novo synthesis of FAs, targeting the FASN enzyme is suggested as a suitable therapeutic strategy for human cancers." (PMID 32155177, 2020). "In HCC cells, miR-1207-5p reduced cancer cell progression by diminishing the Akt/mTOR pathway and its downstream molecular target FASN." (PMID 33050166, 2020). "FASN (fatty acid synthase), the key enzyme in the control of fatty acid synthesis, has received considerable attention as a therapeutic target in cancer including PCa." (PMID 33014785, 2020). "Distinct FASN activity or expression between normal tissues and cancer cells can be exploited and several FASN specific inhibitors have been developed which include cerulenin, C75, orlistat and the recently developed TVB-2640." (PMID 32872164, 2020). "In vitro studies confirmed that the knockdown of FASN in various CRC cell lines hindered the invasive capability of cancer cells, and these results suggested the pro-metastatic role of FASN in CRC tumorigenesis." (PMID 33348563, 2020). "Overexpression of FASN has been described in cancers like gastrointestinal stromal tumors, breast, ovarian, and lung cancers." (PMID 32318352, 2020). "We demonstrate that a decrease in FASN expression is associated with selective induction of CD36 and that this phenomenon is consistent among multiple cancer models." (PMID 32850342, 2020). "This minireview aims to present current knowledge on fatty acid synthase FASN, its roles in cancer cell biology, metabolic reprogramming, and also the current challenges of FASN-targeted therapy." (PMID 32872164, 2020). "Inhibitors of FASN induced cancer cells death directly or sensitized them to chemotherapic drugs, such as 5-fluorouracil and trastuzumab." (PMID 32211323, 2020). "Overall, key players in FA synthesis, such as ATP-citrate lyase (ACLY), acetyl-CoA carboxylase (ACC) and fatty acid synthase (FASN), are elevated in cancer cells." (PMID 32641978, 2020). "One study reported that FASN gene expression was higher in the adjacent non-cancer tissue than in the NSCLC tissue, but authors concluded that it was a weaker predictor of shorter patient survival." (PMID 33194695, 2020). "Attenuation of SREBP-1 or FASN expression leads to inhibition of cell growth and progression, and induction of apoptosis in PCa and other cancers." (PMID 32276528, 2020). "In contrast, FASN is often highly expressed in human cancers and represents a nearly universal phenotypic alteration in most human malignancies, such as breast, prostate, colon, ovary, endometrium, thyroid, esophagus, stomach, lung cancer, etc.." (PMID 33364199, 2020). "Excess glucose is converted into fatty acids in the liver and cancer cells have been shown to activate the fatty acid synthesis pathway by upregulating lipogenic enzymes such as fatty acid synthase (FASN), ACCA, and ACL." (PMID 33212987, 2020). "Fatty acid synthase (FASN) is highly expressed in various types of cancer and has an important role in carcinogenesis and metastasis." (PMID 32699531, 2020). "The EBV‐encoded RNAs have been shown to induce this activation via upregulation of FASN, often affected in cancers, and the low‐density lipoprotein receptor." (PMID 33064888, 2020). "Elevated glucose catabolism is a characteristic of many cancers, and produces an excess of the glycolytic end-product, pyruvate, some of which can be converted to acetyl-CoA and then further converted, through an FASN mediated pathway, to fatty acids." (PMID 32973134, 2020).
cancer (continued). "A positive association between FASN levels and oxidative phosphorylation rates has been reported across various cancer cell types and immune cells through the manipulation of FASN levels." (PMID 32872164, 2020). "All these studies, unequivocally suggest that FASN is an important metabolic target in cancer therapeutics." (PMID 32670883, 2020). "Many malignant carcinomas, including PCa, behave in the same lipid metabolism patterns involving the pivotal enzyme FASN." (PMID 32655718, 2020). "Here, the authors report that FASN promotes anaplerotic shift of the Krebs cycle in cancer cells expressing various oncogenes, and that its inhibition before transformation prevents tumour development and invasion." (PMID 31676791, 2019). "Compared with their radiosensitive counterparts, radioresistant cancer cells also have altered components of energy metabolism, including elevated levels and activity of FASN." (PMID 30774777, 2019). "The enzyme fatty acid synthase (FASN) is the first step for de novo fatty acid synthesis in cancer cells." (PMID 31142021, 2019). "Reduction of the activity of FASN has been found to be an essential event in the tumor growth inhibition, which can be considered to be a novel strategy for cancer treatment." (PMID 30824767, 2019). "In this regard, it has been described a link between FASN downregulation and the reduction of invasion in cancer." (PMID 30913248, 2019). "In this regard, data from The Cancer Genome Atlas dataset showed that FASN gene expression was inversely correlated with BMI (p = 0.034), and median OS was longer in patients with low FASN expression (36.8 v 15.0 months; p = 0.002)." (PMID 31766196, 2019). "Upregulation of fatty acid synthase (FASN) is a common event in cancer, although its mechanistic and potential therapeutic roles are not completely understood." (PMID 31676791, 2019). "Among them, TVB-3166 is a imidazopyridine-based, orally-available, FASN inhibitor, which suppresses de novo palmitate synthesis in vitro and in vivo, and displays antineoplastic activity in several experimental cancer models." (PMID 31921669, 2019). "An increasing number of studies have highlighted the potential function of FASN as both a biomarker and therapeutic target for cancers." (PMID 31122252, 2019). "Increased expression of FASN, SCD1 and SREBP-1c is associated with multiple forms of cancer, and lipogenesis inhibitors that block the activities of FASN9, SCD1 and SREBP-1c have been shown to reduce cancer cell proliferation and induce apoptosis." (PMID 31138790, 2019). "Although in established tumors FASN upregulation has been described as a “cancer autonomous” system to generate its own lipid pools, in the proposed model the requirement of FASN by transforming cells would be unrelated to the enzymatic product." (PMID 31676791, 2019). "Fatty acid synthase, FASN, a key enzyme in the de novo synthesis of lipids, is found to be overexpressed in many cancers." (PMID 31137815, 2019). "FASN has been extensively studied in cancer, but its specific mechanistic relationship with carcinogenesis, and its definitive therapeutic role, have not been completely established." (PMID 31676791, 2019). "FASN is overexpressed in many human cancers, such as prostate cancer, breast cancer, bladder cancer, liver cancer, lung cancer and SCC of the oral cavity." (PMID 31242216, 2019). "RES significantly reduced lipid synthesis through the downregulation of FASN in many cancer cell lines." (PMID 31159437, 2019). "In the same study, EMT induction, in turn, promoted FASN expression to create a positive feedback loop that accelerated cancer progression." (PMID 31027222, 2019). "In the present study, we described a mechanism regarding the role of FASN in cancer, linking the very common upregulation of FASN in cancer to a critical role in acquiring 3D growth properties during transformation, unrelated to its biosynthetic product." (PMID 31676791, 2019).
cancer (continued). "FASN inhibitors and cholesterol-lowering agents are known to induce apoptosis in cancer cells; therefore, they are considered in anticancer drug development." (PMID 31861640, 2019). "Cancer cells adopt “Warburg” like metabolism (i.e., anaerobic glycolysis) sustained by key regulators such as fatty acid synthase (FASN) and ACC." (PMID 31052147, 2019). "Another possible therapeutic target is fatty acid synthase, which is expressed at high levels in cancer cells and leads to more lipogenesis and oncogenic signaling pathways." (PMID 30717356, 2019). "Taken together, all these results suggested FASN/ERK1/2/Bcl-xL was an important signaling pathway in the cancer." (PMID 30931932, 2019). "Fatty acid synthase (FASN) –a key-regulator of de novo fatty acid (FA) synthesis– has been extensively shown to fuel cancer cell proliferation and malignant progression." (PMID 31138183, 2019). "For example, it has been reported that in addition to the markers of de novo synthesis (FASN) different cancer cells also express markers of lipolysis (lipoprotein lipase, LPL) and exogenous FA uptake (CD36)." (PMID 31138183, 2019). "The metabolic products of FASN from endogenous FAs participate in cancer evolution by influencing the expression, activity and location of the proteins produced by cancer cells." (PMID 31242216, 2019). "The inhibition of FASN significantly improves the malignant biological behavior of many cancer cell lines." (PMID 31122252, 2019). "Instead, it can be concluded that fatty oxidation negatively regulates EMT induction in cancer cells, which is consistent with FASN-induced EMT induction, as previously discussed." (PMID 31027222, 2019). "These evidences strongly suggest that FASN inhibitors will play an important role in future therapeutic attempts against cancer, hopefully also against HCC." (PMID 31921669, 2019). "mTORC1 also over regulates fatty acid synthase, an enzyme that favors the rapid increase of cancer cells." (PMID 30909557, 2019). "In some proliferating cells such as in cancer and neuronal progenitors, FASN activity is required to support increased metabolic demands." (PMID 31063129, 2019). "Previous studies have suggested that FASN expression and its activity contribute to the proliferation, metastasis, migration, and invasion of cancer cells." (PMID 31122252, 2019). "Several FASN inhibitors have been tested against cancer in preclinical studies, including cerulenin, Orlistat, C75, Fasnall, TVB-2640, and others." (PMID 31921669, 2019). "Recently, inhibition of FASN has been considered as an attractive target for cancer treatment, including hepatocellular carcinoma." (PMID 30824767, 2019). "Pioneering examples of studies investigating the lipogenic dependency of cancer in recent years include those performed with small molecule FASN inhibitors like cerulenin, an antibiotic isolated from fungal extracts." (PMID 31921669, 2019). "FASN expression correlates with cancer progression, poor therapeutic response to gemcitabine, and survival." (PMID 30755605, 2019). "In the last decade, intense research has been focused on designing or re-purposing FASN inhibitors to block the ability of cancer cells to make their own lipids." (PMID 31142021, 2019). "We also checked another cancer-promoting lipid modifying enzyme, fatty acid synthase (FASN), for which we had both RNA-Seq and protein quantitation data from our proteomics analysis." (PMID 30728898, 2019). "Inhibition of FASN is under evaluation in several clinical trials in cancer patients (NCT03179904, NCT02980029, NCT02595372), after promising preclinical studies in animal models." (PMID 31137815, 2019). "In hypoxic cancer cells, the expression of other enzymes that are involved in de novo lipid synthesis often show similar trends to those of FASN." (PMID 31092908, 2019).
cancer (continued). "FASN expression and the levels of cholesterol are much higher in cancer cells than in normal cells, promoting cell proliferation, drug resistance, and tumor progression." (PMID 31861640, 2019). "In cancer, multiple studies have shown that FASN is strongly upregulated in tumors from breast, prostate, colorectal, bladder, ovary, and lung, especially when characterized by clinical aggressiveness, poor prognosis, and resistance to therapy." (PMID 31921669, 2019). "The pivotal role of fatty acid synthase (FASN) in cancer pathogenesis has led to a great interest in these drugs as anti-tumor candidates but a lipidomic characterization of their effects is lacking." (PMID 30682837, 2019). "Specific examples include elevated rates of lipid synthesis accounted for by increased expression of various lipogenic enzymes, such as fatty acid synthase (FASN), which is strongly correlated with cancer progression." (PMID 31835444, 2019). "Several carcinomas such as breast, colon, lung, prostate, among others, overexpress FASN, suggesting it as a unique onco target." (PMID 30875891, 2019). "Recent studies showed that Fatty Acid Synthase (FASN), a lipogenic enzyme overexpressed in several carcinomas, plays an important role in drug resistance." (PMID 30875891, 2019). "When cancer cells are treated with the inhibitor of fatty acid synthase, the increased protein expression of cyclin B1 was observed." (PMID 30388870, 2018). "Cancer tissue exhibits aberrant lipid biosynthesis ancillary to cancer proliferation via fatty acid synthase (FASN)." (PMID 29963246, 2018). "The increased lipogenesis in cancer is reflected by the overexpression and hyperactivity of lipogenic enzymes, such as FASN and SCD1." (PMID 29552293, 2018). "Inhibition of FASN leads cancer cells to apoptosis, mainly by inhibiting DNA replication and the production of anti-apoptotic proteins." (PMID 29385093, 2018). "ME1 contributes to the cytoplasmic pool of NADPH, a fraction of which is used by Fatty Acid Synthase (FASN), a primary lipogenic enzyme that is upregulated in many cancers and is itself implicated in tumor genesis and metastasis." (PMID 30250042, 2018). "The hypoxic environment can promote stabilization of HIF1α which leads to increased expression of SREBP1 and FASN in the cancer cell line." (PMID 29588626, 2018). "Additional supporting evidence to verify the DNL pathway in regulating cancer cell viability has been shown where the inhibition of FASN by FASN inhibitor‐alcohol extract of clove suppressed the S‐phase DNA replication of HepG2 cells." (PMID 29928578, 2018). "Stable knockdown of FASN is associated with a significant decrease in de novo palmitate synthesis and formation of lipid droplets, suggesting that expression of FASN and its activity significantly affects lipid composition and storage in cancer cells." (PMID 29872506, 2018). "It has been shown that lipid production is critical for cancer cell survival, while the expression of the central lipogenic enzyme fatty acid synthase (FASN) is strongly correlated with cancer progression." (PMID 29434587, 2018). "In cancer cells, FASN confers tumor growth and survival advantages, which appears to necessarily accompany the natural history of most human cancers." (PMID 30619288, 2018). "Strikingly, Orlistat, a FDA-approved anti-obesity drug targeting FASN, exerts a potent anti-tumor activity in various cancers." (PMID 29907133, 2018). "As most normal cells prefer exogenous sources of FAs, targeting FASN has been demonstrated to be a viable approach as it reduces the de novo FA synthesis in cancer cells." (PMID 30186863, 2018). "Orlistat, a FASN inhibitor, increases the sensitivity to all drugs, suggesting that FASN can be a new target in drug resistant cancers." (PMID 30456204, 2018). "FASN, the most extensively investigated lipogenic enzyme in cancer, is responsible for the synthesis of palmitate (C16:0) from acetyl-CoA and malonyl-CoA in the presence of NADPH." (PMID 30445800, 2018).